CD14 (CD14 molecule)
Diseases named in the same sentence as CD14 in open-access papers (continued):
Sharing a sentence is not in itself a finding about the gene and the disease.
tumor (continued). "In a previous study, CD14+ cells detected in peripheral blood of patients with advanced stages of HCC were characterized as the M2b phenotype and were found to be a significant contributor to tumor growth promotion." (PMID 32824016, 2020). "We here showed that the phenotype of tumour-induced CD14+ DCs was not obtained in parallel intra-donor 2D co-culture experiments." (PMID 32488012, 2020). "There are many data reporting the pro-angiogenic role of CD14+CD16+ non-classical monocytes either in physiological conditions or in the tumor microenvironment." (PMID 30845779, 2019). "To further examine the role of monocytes and pDC for anti-tumor immunity, we repeated PBMC-CM toxicity, NK cell activation and degranulation assays, as well as T cell priming experiments but depleted CD14+ monocytes, pDC, or both, from the whole PBMC population." (PMID 31262361, 2019). "CD14+-depleted single cells from both infiltrated and non-infiltrated tumor spheroids were then analyzed by mRNA seq." (PMID 30615637, 2019). "The analyses showing that neither the number of tumor cell spheroids of tumor cells nor the abundance of TAMs (CD14+ cells of total leukocyte count) in ascites was correlated with the concentration of any of the LPA species (data not shown)." (PMID 30353652, 2019). "Monocytes that have diminished or no HLA-DR expression, called CD14+HLA-DRlo/neg monocytes, have emerged as important mediators of tumor-induced immunosuppression." (PMID 31191529, 2019). "As expected, CD14+SIRPαhi cells possessed properties of typical Mo/MΦs including a typical phenotype of Mo/MΦs, being able to migrate in response to MCP-1, phagocytosing latex beads and tumor cells, and suppressing T-cell function." (PMID 31611550, 2019). "A similar result was obtained when a macrophage signature comprising a subset of eight widely used markers (CD14, CD105, CD11b, CD68, CD93, CD33, IL-4R and CD163) for the mononuclear phagocyte system was used to identify tumours highly infiltrated by macrophages." (PMID 29921315, 2018). "IHC analysis showed that these areas were positive for CD209, CD14, and the tumour marker WT1, whereas they were negative for the lineage-specific marker CD45 (data not shown)." (PMID 30510965, 2018). "Further IHC exams stated that elements such as positive markers for histiocytes and monocytes (CD68+++ and CD14+), Langerine- and CD1a – could exclude HCL or another tumor with dendritic undetermined cells, that are usually Langerine -, but CD1a+." (PMID 29450403, 2017). "In contrast, there was no significant increase in CD14+ M-MDSC in tumor compared to normal tissue (NT; 0.01 ± 0.01 vs TT; 0.05 ± 0.02)." (PMID 28283696, 2017). "The percentages of IL-10+CD14+CD169+ circulating monocytes and TIMs in total CD14+CD169+ cells from CRC patients were significantly higher than that from the non-tumor subjects (3.79% vs. 0.76%, P<0.0001 for circulating monocytes; 7.12% vs. 1.23%, P<0.0001 for TIMs." (PMID 26509874, 2015). "Next, we stratified the patients, according to their tumor pathological TNM stages and we found that the percentages of CD14+CD169+ circulating monocytes were significantly lower in the patients with early stage of CRC than those with advanced stage of CRC (11.81% vs. 15.91%, P = 00003)." (PMID 26509874, 2015). "Given that CD169 is an adhesion molecule it is possible that CD14+CD169+ circulating monocytes may migrate and be activated in the tumor environment to regulate the progression and metastasis of CRC." (PMID 26509874, 2015). "Ex vivo CD14/IL-12 double-labeling experiments identified that physical activity increased the quantity of CD14+/IL-12+ cells, compared with that of the no tumor/non-trained control group (P<0.0001)." (PMID 24520305, 2014). "IHC revealed a tumor that was CD14, S100, and CD45, smooth muscle actin positive and negative for CD21, CD35, CD20, CD10, and CD3." (PMID 25405526, 2014).
tumor (continued). "Among PB monocytes, CD14+CD16++ subset (nonclassical monocytes) exhibits a higher cytotoxicity towards tumour cells." (PMID 23180014, 2013). "In addition to CD14-and TLR4-dependent LPS-signaling, activation of the EGFR seems to be a crucial element of the observed tumor cell proliferation." (PMID 22923191, 2013). "Our previous studies on the adherence of mononuclear cells infiltrating CC531 liver tumors revealed a predilection of CD14 MHC II-positive cells (that is, TAMs) for liver adenocarcinoma metastases, with the highest propensity being for adherence to tumor stroma." (PMID 24274644, 2013). "The fact that intermediate monocytes may express pro-angiogenic (and thus potentially pro-tumor) factors such as TIE2, endoglin or VEGFR-2 has prompted us to investigate a particular subset of intermediate monocytes, the CD14++CD16+TIE2+ TEMs." (PMID 22973451, 2012). "To model the native ascites tumor environment as closely as possible in vitro, we analyzed bulk ascites cell pellets, which in addition to CD8+ and CD4+ T cells, contained resident tumor cells, Tregs, B cells, NK cells, and CD14+ cells." (PMID 21203522, 2010). "A recent study has documented that versican, a large extracellular matrix proteoglycan, can activate tumour-infiltrating myeloid cells through TLR-2 and its coreceptors TLR-6 and CD14 and elicit the production of proinflammatory cytokines including TNF-alpha that enhance tumor metastasis." (PMID 20652007, 2010). "In our setting, neither the inhibition of NKG2D in positively isolated CD56+, CD14+ or CD3+CD56- cell populations nor the inhibition of the TRAIL in positively isolated CD14+ cells had any effect on delNS1 induced tumor cell killing." (PMID 19125202, 2009). "Additionally, in PTC patients, we found that the percentages of CD45+ lymphocytes and HLA-DR+CD14+ monocytes were higher in tumor tissue compared to non-tumoral tissue and peripheral blood." (PMID 40731885, 2025). "By relying on a limited number of proteomic markers, studies using CD14 or even CD45 alone to identify tumor-macrophage hybrids may erroneously include non-fusion cells in their analysis." (PMID 40707771, 2025). "Non-tumor components included endothelial cells (expressing VWF, CDH5, ECSCR, SLCO2A1, and MYCT1), pericytes (marked by RGS5, MCAM, and PDGFRB), normal oligodendrocytes (showing PTGDS, MBP, TF, and MOG expression), and TAMs (identified by CD14, AIF1, FCER1G, FCGR3A, TYROBP, and CSF1R)." (PMID 41394801, 2025). "Although this study only evaluated transfer of CD45 between T cells and TNBC cells, our FFPE data suggest that TNBC cells may also acquire CD45 from macrophages, NK cells, and other types of immune cells as evidenced by expression of immune cell markers CD14, CD56, and CD68 on tumor cells." (PMID 40183054, 2025). "Nonetheless, cancer-associated macrophage-like cells (CAMLs), which may also be identified as hybrids due to their multinucleated structure and expression of CD14+, CD45+, cytokeratin+, and EpCAM+ markers, have been observed to cluster with CTCs at primary tumour sites." (PMID 39967663, 2025). "However, analysis of all three immune markers simultaneously revealed that both intraepithelial CD3+ T cells and the intraepithelial CD14+rest− monocytes were the only independent prognostic markers, irrespective of tumor stage and molecular subtype." (PMID 38954042, 2024). "We show that expression of classical macrophage-related molecules such as CD14, CD163, CD68 and several molecules involved in the function, differentiation and recruitment of macrophages in VS tissue using RT-qPCR, many of which show a correlation to VS tumour volume." (PMID 38480935, 2024). "The absence of CD14-positive cells within the tumour epithelium in ACP is unexpected as the β-catenin-accumulating epithelial whorls (cell clusters) express a variety of chemo-attractant cytokines (e.g., members of the CCL and CXCL family of chemokines including CCL2, CXCL1, CXCL3, CXCL11)." (PMID 39127699, 2024).
tumor (continued). "In conclusion, we show that “DC3-like” CD14+ DCs can arise from cDC2s but not from monocytes in response to tumor-derived cues, which highlights that further delineation of the tumor-induced CD14+ DC and DC3 lineage is essential to precisely define the DC family." (PMID 38242119, 2024). "The macrophage populations, including subsets such as CD14+ and P2RY12+ cells, which are indicative of TAMs of peripheral and cerebral origin, respectively, were found to constitute a considerable fraction of the tumor mass and CD45+ cell population, consistent with literature findings." (PMID 38594259, 2024). "Lastly, while we used multiplex immunofluorescence to validate the presence of CD14+APOE+ cells and MMP7+ tumour cells, additional validation using other complementary techniques such as flow cytometry or single‐cell RNA sequencing could provide a more robust confirmation of our findings." (PMID 39187937, 2024). "MRC1+ macrophages facilitate tumour recurrence following chemotherapy, and tumour biopsy samples from cancer patients who received neoadjuvant therapy had a much larger infiltrate of CD45+CD11b+CD14+ macrophages than those from patients who received only surgery." (PMID 38982317, 2024). "Monocyte subpopulations were characterized as CD16hi (CD16hi-Mo) which are known as non-classical monocytes, and tumor-inflammatory monocytes (TIMo) which had high expression of CD14, a classical monocyte marker as well as the highest expression of an inflammatory gene signature." (PMID 36750562, 2023). "By isolating CD11b+CD14+CD163+ macrophages from normal, peritumor, and intratumor tissues and performing RNA sequencing, we found that macrophage TMEM176B expression levels were lower in normal tissue but higher in tumor tissue, inversely correlating with the expression of CD146." (PMID 37308559, 2023). "Also, the ΔΨm of CD14+ monocyte was significantly decreased in the gastrointestinal cancer patients without anti-tumor treatments." (PMID 36765353, 2023). "From each patient, blood, dissociated liver, and tumor tissues were subjected to Ficoll gradient centrifugation to separate mononuclear immune cells from which memory CD4+ T cells, memory CD8+ T cells, CD56+ NK cells, and CD14+ monocytes/macrophages were sorted to a purity of >98%." (PMID 37388918, 2023). "The identified PhenoGraph clusters were assigned to seven major populations: tumor cells (panCK+), CD4+ T cells (CD45+CD3+CD4+), CD8+ T cells (CD45+CD3+CD8+), B cells (CD45+CD20+), blood vessel (CD31+ and/or aSMA+), fibroblasts (collagen+), and myeloid cells (CD45+CD14+)." (PMID 38125025, 2023). "Subtype C1 apoptotic CD14 is generally enriched in tumor tissues (paired t-test p-value = 0.021), especially in ESCA (paired t-test p-value = 0.0012) when compared to the matching normal tissues, while C0 CD16 mainly resides in non-tumor tissues of the same type (paired t-test p-value = 0.0015)." (PMID 36641532, 2023). "In addition, under normal culture conditions, the presence of CD14+ cells did not alter tumor growth kinetics." (PMID 36139660, 2022). "The significant upregulation of CA12 in and on tumor-purified monocytes was further confirmed by immunoblotting and flow cytometry analysis, which also showed that all the other CD14– cellular components expressed none to very low levels of CA12 regardless of their tissue area of origin." (PMID 35362480, 2022). "Additionally, these data are of significant importance, as the basic principle of the EDIM technology, namely the phagocytosis of the tumor cells by CD14+/CD16+ monocytes and the subsequent detection of epitopes in CD14+/CD16+ monocytes by flow cytometry, has thus been demonstrated." (PMID 36009359, 2022). "Nearest neighbour analysis demonstrated that the median distance from the CD14+ HLA-DR− cells to CD3+ cells at the invasive margin was either much less (Samples 1,3,4 and 5) or the same (Sample 2) as the distances from the CD14+ HLA-DR − cells to the CD3+ cells in the centre of the tumour." (PMID 34727230, 2022).
tumor (continued). "Importantly, CD14+ cells added to coculture shortly before cisplatin exposure did not result in improved tumor recovery in H889 or in H1581." (PMID 36139660, 2022). "Analysis of bulk tumour mRNA displayed a strong correlation between ACTA2, a marker of MSCs, and matrix remodelling enzymes (MMP2), ECM proteins (VCAN, FN1, COL1A1), immunomodulatory molecules (Serpine1, CXCL12), innate immune cell markers (CD14, ITGAX) and adaptive immune cell markers (CD4)." (PMID 34885111, 2021). "As non-classical/intermediate monocytes represented the predominant CD16+ cell population after NK cells in PBMC, we determined whether depletion of monocytes from PBMC using a negative CD14 magnetic bead-mediated selection impacted tumor growth inhibition." (PMID 34771609, 2021). "CD14 is also a marker of monocytic myeloid-derived suppressor cells (M-MDSCs), and its expression may suggest increased distribution of this MDSC subpopulation in the tumor milieu." (PMID 33625532, 2021). "Strong staining for CD14 was detected in non-tumour tissue with less label in tumour tissue." (PMID 33906633, 2021). "In addition, we identified a unique population of CD14+ positive monocytes which were absent in the PBMCs of exceptional survivors, suggesting a potential role for these cells in promoting tumor progression." (PMID 32523648, 2020). "High levels of CD14+CD204+ cells in the pulmonary vein (PV) of patients with NSCLC were identified in cases of early recurrence and were positively related to the expression of CD204 in the tumor stroma of 207 stage I lung adenocarcinoma patients from Japanese cohort." (PMID 33194645, 2020). "In addition, depletion of CD14+ and CD45RA+ cells in the tumor regions was observed." (PMID 31164128, 2019). "It is interesting that ATX, LPAR1, and LPAR5 are higher in the immune-high tumor (Cd14-, Cd68-, Cd164-, and Cd3E-high) group, but LPAR2.3 are higher in the immune-low group, suggesting the complex regulatory roles of the ATX–LPA axis in the tumor–immune system interaction." (PMID 31658655, 2019). "Importantly, the number of CD14+ cells isolated from the tumor and blood samples did not correlate with the tumor volume, and histological analysis revealed an infiltration of a diverse number of CD14+ cells in tumors of different sizes." (PMID 31155685, 2019). "Perhaps the simplest and most efficient way to measure CD14+HLA-DRlo/neg monocytes is by flow cytometry of peripheral blood; therefore, acquisition of tumor biopsies which may not always be available from patients is unnecessary." (PMID 31191529, 2019). "Multigene expression analysis by qRT–PCR revealed a strong correlation between the expression of human monocytic markers CD14 or CD16 and diverse IFN-I-related genes such as IFNB1, USP18 and IRF7, indicating that human monocytic infiltrates can produce IFN-I within human tumour tissues." (PMID 28248314, 2017). "Analysis of potential biomarkers showed reduction of CD14+ monocytes in peripheral blood suggesting a PD effect of RG7356; one of the proposed modes of action is to trigger direct antitumor effects by activating CD68+ macrophages via Fc/FcgR interaction to phagocytose CD44-positive tumor cells." (PMID 27507056, 2016). "Furthermore, mice in the tumor/non-trained group exhibited a sharp reduction in CD14+/IL-12+ cell frequency (P<0.0001), when compared with the control group." (PMID 24520305, 2014). "In order to evaluate whether MDSCs belong to the tumor clone or normal residual cells, in 3 patients we analyzed BCR/ABL expression in both CD11b+CD33+CD14-HLADR- and CD14+HLADR- subpopulation cells and all samples showed the oncoprotein expression in both the two subsets (data not shown)." (PMID 25014230, 2014). "Isolated CD14-positive monocytes did not induce tumour lysis in a 4 h assay." (PMID 23918228, 2013).
tumor (continued). "Importantly, reduction of tumor load by neoadjuvant chemotherapy led to normalization of the migratory DDC subset distribution, providing evidence for tumor involvement in the observed aberrant migration of predominantly CD14+ DDC." (PMID 23875023, 2013). "However, the addition of apoptotic tumor cells enhanced the decrease in CD14 expression while the presence of viable CTCL cells was not as effective in stabilizing the monocyte to DC conversion." (PMID 17291350, 2007). "Moreover, the expression level of CAXII mRNA increased in tumor-infiltrating monocytes but not in other CD14+ cell components in both tumor tissue and non-tumor liver tissue, indicating that CAXII might contribute to HCC progression." (PMID 37006233, 2023). "Furthermore, the amount of tumor compounds phagocytized by CD14+/CD16+ monocytes, could not be determined." (PMID 36009359, 2022). "This method is based on macrophages (CD14+/CD16+), the number of which may be elevated in the blood of patients with diseases such as cancer, and which phagocytose parts of neoplastic cells and possibly extracellular vesicles (EVs) or circulating tumour cells (CTCs)." (PMID 35864157, 2022). "Interestingly, monocytes show a similar polarization pattern, which relies on the expression of CD14 and CD16; in particular, we recognize: classical (CD14+CD16−), intermediate (CD14+/− CD16low), and non-classical monocytes (CD14−CD16+), the latter being considered a tumor-promoting phenotype." (PMID 34203150, 2021). "Interestingly, we observe that the presence of a tumour within the engineered TME leads to the transformation of normal immunostimulatory cDC2s into CD14+ DCs, with a phenotype matching their in vivo counterpart and an impaired ability to stimulate T-cell proliferation." (PMID 32488012, 2020). "Initially, we identified both monocytes (CD14+) and pDC as cell populations which expressed significantly more ICAM-1 than NK cells, CD4+ and CD8+ T cells, therefore, we hypothesized that these two cell types may act as key regulators of CVA21-mediated anti-tumor immunity." (PMID 31262361, 2019). "Furthermore, CTL priming assays (performed without the addition of autologous mDC) also revealed the importance of pDC, as the absence of CD14+ did not significantly decrease the production of tumor-specific CTLs; however, removal of pDC significantly reduced levels of tumor-specific CTL." (PMID 31262361, 2019). "Furthermore, these infiltrated CD14+ cells exhibited high PD-L1 expression, which allowed them to interact with CD3+PD-1+ T-cells, and might provoke the phenomenon known as ‘T-cell exhaustion’ thus impairing the T-cell response to tumour expansion." (PMID 30285662, 2018). "The recently characterized BDCA1+CD14+ immunosuppressive cells combine both aspects; their presence in DC vaccines may directly hamper vaccine efficacy, whereas, in patients, BDCA1+CD14+ cells may suppress the induced immune response in an antigen-specific manner systemically and at the tumor site." (PMID 30235890, 2018). "As supernatants of TRAIL-treated cells were also able to polarize human CD14+ cells toward HLA-DRlo/neg CD206+ cells in vitro, it is conceivable that TRAIL-induced cytokines may not only recruit myeloid cells to, but also promote their polarization within, the tumor microenvironment." (PMID 28212753, 2017). "Notably, we did not observe the expression of CD68, CD204 and CD206 on CD14+HLA-DR−/low MDSC from OC, making them distinguishable from tumor-associated macrophages (TAM) with alternative polarization (M2) which has been well characterized and described to be correlated with RFS of OC patients." (PMID 29100353, 2017). "To determine whether activation of Wnt signaling could induce osteogenic differentiation of tumor stromal cells, we treated CD14-negative stromal cells grown in osteogenic media with the GSK3β inhibitor SB415286, which activates β-catenin and up-regulates canonical Wnt signaling." (PMID 23922683, 2013).